IL2 (interleukin 2)
Diseases named in the same sentence as IL2 in open-access papers (continued):
Sharing a sentence is not in itself a finding about the gene and the disease.
metastatic carcinoma (continued). "Interestingly, the increased levels of an anti-cancer cytokine, IL-2, are significant for treating metastatic cancers by inhibiting tumor growth via the activation of lymphocytes." (PMID 36651944, 2023). "Alginate-based encapsulation systems for delivery of native IL2 as a successful monotherapy for metastatic cancers is a starting point for encapsulated cell therapies and is essentially only limited by the size of the pores restricting efficient diffusion into the surrounding space." (PMID 35235346, 2022). "Although high dose of IL-2 has been used for immunotherapy against metastatic cancer, low-dose of IL-2, however, preferentially stimulates Tregs and has shown a great potential of success in Treg-based immunosuppressive strategies against autoimmune and inflammatory diseases." (PMID 35757774, 2022). "However, at lower doses than those used for metastatic cancer therapy, IL-2 stimulates T reg cells to control NK cell proliferation and cytotoxicity." (PMID 33407826, 2021). "Furthermore, a high-dose treatment of IL-2 has been shown to be beneficial in treating metastatic cancer because of an increased activity of natural killer cells towards tumors." (PMID 34685775, 2021). "IL-2 is used in the treatment of metastatic cancer but induced severe pruritus." (PMID 27195291, 2016). "Importantly, a high dose of IL-2 could produce lethal toxicity and lead to the destruction of cells making high-dose IL-2 efficacious in treating metastatic cancer due to increasing the activity of natural killer cells toward the tumors." (PMID 34685775, 2021). "Finally, we summarize the clinical applications of IL-2 and IL-15 in metastatic cancer." (PMID 33266177, 2020). "Notably, human Vγ2Vδ2 T cells can be selectively expanded in vivo by zoledronate, a clinical drug widely used for treatment of bone-related disease, and that zoledronate/IL-2 expansion of Vγ2Vδ2 T cells has been tested as therapeutic regimen for treatment of metastatic cancers." (PMID 23966854, 2013). "The cytokine IL‐2 is central to protective immunity and has shown a potent capacity to induce T‐cell growth in vitro and is an FDA‐approved drug for multiple metastatic cancers." (PMID 36069650, 2022). "Based on personal communication, we know that L19-interleukin 2 (IL2) (darleukin; 15 MIO IU) has shown promising results in a phase I trial (NCT02086721) when combined with SABR in oligo-metastatic cancer patients." (PMID 32539805, 2020). "Therefore, a new IL-2 mutant that reduces Treg proliferation would greatly improve IL-2 based immunotherapy and could bring significant benefits to patients suffering from metastatic cancer." (PMID 30250191, 2018). "Arrhythmia has been reported as a side effect of treatment of patients with metastatic cancer with TNF-α, IL-2, and IFN-γ." (PMID 26284064, 2015). "One study found that patients with metastatic cancers that showed no response to IL-2 treatment had significantly higher ICOS+ Tregs, an especially proliferative and immunosuppressive subset, than patients who responded to treatment." (PMID 38545115, 2024). "Besides IL-2, L19 was also coupled to IL-12 and tumour necrosis factor (TNF) α, revealing equally promising results in solid metastatic cancers, in particular for L19-TNF in combination with L19-IL2." (PMID 32481570, 2020). "For example, interleukin-2 (IL-2) and/or alpha-interferon (α-IFN) have been widely used in clinical study to combine with cisplatin, vinblastine, or 5-fluorouracil for the patient with metastatic cancer, which resulted in a synergistic therapeutic efficacy." (PMID 24619193, 2014). "Here, the authors, by integrating unmutated human IL-2 in the antigen binding groove of an anti-IL-2 monoclonal antibody, generate a CD122-biased fusion protein that prevents binding of IL-2 to CD25 and promotes anti-tumor immune response in several preclinical metastatic cancer models." (PMID 33353953, 2020).
metastatic carcinoma (continued). "Finally, pretreatment high levels of CRP predict both the lack of IL-2 activity on tumour objective response and its efficacy on overall survival in metastatic cancer patients." (PMID 17953739, 2007). "On these bases, a study was performed to evaluate the influence of a Kriya Yoga program in a group of metastatic cancer patients who did not respond to previous anticancer conventional therapies and who were treated with supportive care alone, MLT alone, low-dose IL-2 alone, or IL-2 plus MLT.." (PMID 21654973, 2011).
pneumonia (41 papers, 2011 to 2025). An acute, acute and chronic, or chronic inflammation focally or diffusely affecting the lung parenchyma, caused by an infection in one or both of the lungs (by bacteria, viruses, fungi, or mycoplasma.). "It was reported that the severity of pneumonia in critically ill patients was associated with IL-2-induced lymphocytopenia." (PMID 33996639, 2021). "In lung resection surgery patients, post-operative pneumonia was associated with a perioperative decrease in IL-2 mRNA (P < 0.0001) and IL-7 mRNA (P = 0.003)." (PMID 21711552, 2011). "• The overexpression of cytokines (i.e., TNF-α, IL-2, IL-10, IL-1, and IL-6) leads to development lung damage, cell death, severe pneumonia, ARDS, lung fibrosis, local or systemic thrombosis and multiple organ failure." (PMID 35422702, 2022). "A multiplex-biometric immunoassay showed that pneumonia cases had higher levels of serum cytokines (G-CSF, IL-2, IL-6, IL-10, IL-18, IP-10, MCP-3, and TNF-α) than bronchitis cases." (PMID 36119044, 2022). "Compared with the HMPV pneumonia group and healthy control group, the former had a significantly lower level of IL-2 and higher levels of IL-4, IL-6, IL-10, and IFN-γ." (PMID 36496397, 2022). "When compared with the healthy children, children who were infected with HMPV pneumonia had a significantly lower level of IL-2 (p < 0.001) and higher levels of IL-4 (p < 0.001), IL-6 (p = 0.001), IL-10 (p < 0.001), and IFN-γ (p < 0.001)." (PMID 36496397, 2022). "In contrast, during the recovery period of the pneumonia group, such as for cases P1, P2, and U1, there were decreases in certain cytokines, such as IL-2, IL-6, MCP-3, and TNF-α." (PMID 36119044, 2022). "Reduces levels of B lymphocytes, CD8+ proportion, IL-1α, IL-1β, IL-2, IgM, IgG, etc., reduces quality of thymus, spleen and lung of pneumonia mice, and increase CD4+/CD8+ and NK cell proportion." (PMID 32848729, 2020). "Further studies found that SFJDC had a significant immune regulatory function, reducing levels of B lymphocytes, CD8+ cells, interleukin-1α (IL-1α), IL-1β, IL-2, IgM, and IgG to improve lung function in mice with pneumonia." (PMID 32848729, 2020). "Zinc supplementation showed benefits, shortening the duration of oxygen desaturation, tachypnea, and clinical symptoms in children with pneumonia, showing a Th1 response with the increase of IFNγ and IL-2 cytokines." (PMID 31803694, 2019). "Does over-expression of IL-2 in brainstem neuronal centres together with silent pneumonia, contribute to breathing changes seen during the dying phase?" (PMID 28384249, 2017). "Therefore, further analysis is needed to explore the role of the IL-2/IL-2R pathway in different contexts of pneumonia." (PMID 40406149, 2025). "Besides, another study also explored the immune reactions in Chlamydia psittaci pneumonia and they found psittacosis cases with pneumonia had higher levels of serum cytokines (G-CSF, IL-2, IL-6, IL-10, IL-18, IP-10, MCP-3, and TNF-α) than bronchitis cases." (PMID 40236451, 2025). "However, research has shown that IL-2 transfusion can induce prompt and intense pulmonary inflammation through natural killer cells, which is in accord with our findings that IL-2 levels were higher in the severe pneumonia group." (PMID 34692846, 2021). "The levels of serum cytokines including CXCL10, IL-2, and TNF-α appeared to be correlated with the severity of pneumonia." (PMID 36949406, 2023). "Elevated concentrations of both pro- and anti-inflammatory plasma cytokines were observed in the pneumonia group, including G-CSF, HGF, IL-1b, IL-1RA, IL-2, IL-2Ra, IL-6, IL-10, IL-18, IP-10, monocyte chemoattractant protein-3 (MCP-3), and TNF-α." (PMID 36119044, 2022). "Acute pneumonia increased the expression of TNF-α, IFN-γ, IL-6, IL-2 and IL-17 genes, and decreased the expression of Foxp3, IL-10, and TGFβ1 genes in lung tissue homogenate of mice." (PMID 35782123, 2022).
pneumonia (continued). "After 2 and 4 months, a delayed-type hypersensitivity (DTH) response, the degree of pneumonia-affected lung tissue, CFU, T cell count, and cytokine expression (IL-2, IL-4, IL-10, and IFN-γ) were determined." (PMID 35562916, 2022). "It has a therapeutic impact on pneumonia model rats by reducing B lymphocytes, CD8+ ratio, and elevated levels of IL-1α, IL-1β, IL-2, IL-10, TNF-α, IFN-α, IFN-γ, IgM, IgG, CD4+/CD8+, and NK cells." (PMID 36388945, 2022). "Then, the expressions of 25-OH-VD, VDR, TGFβ, IL-2, IFN-γ, TNFα, IL-1β, Ca2+, PCT, CRP, and IL-6 in mild pneumonia, severe pneumonia, and healthy controls were determined using qRT-PCR, western blot, ELISA, and calcium colorimetry assay." (PMID 34643152, 2021). "In addition, IL-2, IL-4, IL-6, IL-10, TNF-α, and IFN-γ levels were elevated by varying amounts depending on the type of pneumonia." (PMID 41011430, 2025). "We found that high levels of IL-6, IFN-γ, and IL-2 and low levels of IL-5, IL-25, IL-17A, and IL-22 were found in the severe pneumonia group compared to the nonsevere pneumonia group." (PMID 34692846, 2021). "Serum IL-6, sCD40L, IL-5 and IL-2 further rose in time point B in patients who developed severe pneumonia, while no such change was seen in patients with DHF." (PMID 33199778, 2020). "Measurement of inflammatory cytokine levels using ELISA showed that IL-1β, IL-6, TNF-α, IL-2, IL-8, IL-12, and IFN-γ levels were significantly enhanced, while IL-10 levels were significantly reduced in the lung homogenates of Spn-induced pneumonia mice, compared with the normal mice." (PMID 32460745, 2020). "Based on IL-2 in migraine group [2.16 (1.62) pg/mL], in encephalitis with headache group [1.67 (1.22) pg/mL], and in pneumonia without headache group [2.18 (3.07) pg/mL], there were statistical differences in the overall distribution of IL-2 among the three groups (H = 6.80, p = 0.033)." (PMID 38356891, 2024). "Significantly higher plasma levels of IL-2, IL-7, IL-10, G-CSF, IP-10, MCP-1, MIP-1α, and TNFα were found in patients with severe pneumonia developing ARDS compared to non-ICU patients showing pneumonia without ADRS." (PMID 34578468, 2021). "To better understand the relationship between MR1/5-OP-RU tetramer staining, CDR3α usage and MR1-dependent T cell activity, we sorted MR1/5-OP-RU positive cells from the BAL of an available individual with non-TB pneumonia and performed limiting dilution cloning using anti-CD3 and IL-2 stimulation." (PMID 31231693, 2019). "Significantly higher plasma levels of IL-2, IL-7, IL-10, G-CSF, IP-10, MCP-1, MIP-1α, and TNFα were found in patients with severe pneumonia developing ARDS and requiring ICU admission and oxygen therapy compared to non-ICU patients showing pneumonia without ADRS." (PMID 33362782, 2020). "Notably, significantly higher plasma levels of IL-2, IL-7, IL-10, G-CSF, IP-10, MCP-1, MIP-1α, and TNFα were found in patients with severe pneumonia developing ARDS and required ICU admission and oxygen therapy compared to non-ICU patients showing pneumonia without ADRS." (PMID 34639132, 2021).
AIDS (40 papers, 2004 to 2025). A syndrome resulting from the acquired deficiency of cellular immunity caused by the human immunodeficiency virus (HIV). "The keynote is by distinguished Professor Robert Gallo, who co-discovered HIV as the cause of AIDS, revealed nearly all of the virus’ access gene functions, discovered interleukin-2, HTLV-I, II, and the herpes virus link to Kaposi’s sarcoma." (PMID 40313365, 2025). "Clerici and Shearer observed that the progression of HIV infection in AIDS is characterized by the loss of IL-2 and IFN-γ production and the increase in IL-4 and IL-10." (PMID 39062756, 2024). "In a study involving macaques with SIV-induced encephalitis, rapid progression to Acquired Immune Deficiency Syndrome (AIDS) correlated with an increase in IL-1β, IL-2, IL-6, IL-10, and TNF-α." (PMID 34784367, 2021). "Because of the higher risk of developing opportunistic infections or AIDS and non AIDS-related events, patients with very low immunologic competences may benefit from IL-2 adjuvant treatment more than patients who fully respond to antiretrovirals." (PMID 21124762, 2010). "In the case of acute HIV-1 subtype B and C infections, the pro-inflammatory “cytokine storm” activation contributes to CD4+ T cell lymphopenia and prevention of IL-2 producing memory CD4+ and CD8+ T cells, which lead to the development of the acquired immune deficiency syndrome (AIDS)." (PMID 36313221, 2022). "It has been reported that acquired immune deficiency syndrome patients with decreased levels of DHEA-S show excessive cytokine production by Th2 cells (IL-4, IL-5, IL-6, and IL-10) and suppression of other cytokines (IL-2, IFN-γ, IL-12)." (PMID 29694639, 2018). "The hyper inflammatory response caused by IL-2/anti-IL-2 treatment in our model could also resemble aspects of the immune reconstitution inflammatory syndrome (IRIS) that is frequently seen in Mtb-infected AIDS patients on ART after recovery of the immune system begins." (PMID 27391012, 2016). "In the first clinical trials, in the 1980s, of recombinant human IL-2 in primary immunodeficiency, AIDS, and cancer, patients almost invariably developed eosinophilia, accompanied by high IL-5 titers." (PMID 35699942, 2022). "IL-2 production declines and IL-2-producing T cells is impaired in chronically HIV-1-infected patients, as indicated by loss of CD4+ T cells and progression to AIDS." (PMID 31379845, 2019). "IL-2 has been intensively studied and shown to lower the rate of opportunistic infections in AIDS patients and reduce bacterial abscess after CLP surgery in mice." (PMID 30379932, 2018). "During the development of ART, recombinant IL-2 has been trialed as adjunctive AIDS treatment by boosting CD4+ T cell numbers during ART." (PMID 27391012, 2016). "Further studies are warranted to fully appreciate the clinical relevance of CD8+ Tregs in AIDs and the efficacy of IL-2 treatment." (PMID 25926835, 2015). "AIDS Clinical Trial Group (ACTG) study A5051 was an open-label study that explored continuation therapy with IL-2 for patients who had participated in A328." (PMID 20687947, 2010). "Based on this property, IL-2 was also used for the augmentation of T-cell responses in vivo in cancer or AIDS patients." (PMID 19603070, 2009). "In contrast to long-term non-progressors, central memory CD8+ T cells capable of producing IL-2 are only rarely detected in viremic individuals progressing rapidly to AIDS, suggesting that IL-2 production plays an important role in CD8+ T cell function." (PMID 18648514, 2008). "IL-2, a critical cell growth factor, enhances T-cell proliferation and the formation of effector and memory T cells, and has been targeted for therapeutic interventions in tumours, AIDS, and organ transplantation." (PMID 39239046, 2024). "Impaired IL-2-producing T cells was one of the first functional defects observed in chronically HIV-1-infected patients, which predicts loss of CD4+ T cells and progression to AIDS." (PMID 29636753, 2018).
AIDS (continued). "It is not clear whether this higher immune activation and inflammation impact the clinical outcome negatively in the long-term follow-up, but the only death, due to a non-AIDS defining cancer, was noted in the IL-2 group." (PMID 26186440, 2015). "One year after seroconversion, neither the absolute number of single IFNγ producing, nor of single IL-2 producing nor of double IFNγ+IL-2 producing Gag-specific CD8+ T cells were significantly associated with AIDS-free survival time." (PMID 18648514, 2008). "Furthermore, a demonstrated activity of IM862 in AIDS-related Kaposi's sarcoma together with minimal toxicity, especially with regard to the many side effects encountered with IL-2 and IFNα, prompted us to initiate this phase II trial." (PMID 15354209, 2004). "Multiple recombinant cytokines have been approved by the Food and Drug Administration (FDA) including IL-2 for the treatment of advanced renal cell carcinoma (RCC) and IFN-α for the treatment of hairy cell leukemia and Acquired immunodeficiency syndrome (AIDS)-related Kaposi’s sarcoma." (PMID 32998419, 2020). "Kaplan-Meier survival analysis and Cox proportional hazard models showed that frequencies of cytokine-producing Gag-specific CD8+ T cells (IFNγ, IL-2 or both) shortly after seroconversion were neither associated with time to AIDS nor with the rate of CD4+ T-cell decline." (PMID 18648514, 2008). "In 1976, he and his colleagues discovered Interleukin-2, a growth factor now used as therapy in cancer, autoimmunity, and HIV/AIDS." (PMID 40313365, 2025). "At the same time, the secretion of cytokines such as IFN-α, IL-2, IL-4, IFN-γ, and TNF-α, are beneficial to delay the disease progression of AIDS." (PMID 35211115, 2022). "Studies have suggested that Blastocystis infection increases the level of IL-2 in HIV-infected persons, changes the Th1/Th2 balance, and accelerates the conversion of HIV infection to AIDS." (PMID 33380335, 2020). "This is in contrast to A328, which showed an apparent decrease in AIDS-defining and HIV-related infections in the IL-2 treated group." (PMID 20687947, 2010). "The AIDS Clinical Trials Group has completed a trial (#5024), which compared ALVAC (vCP1452) to cycles of high-dose IL-2, versus their combination in chronically infected participants." (PMID 17260026, 2007). "In a study performed over 25 years ago, no people with AIDS who received IFNγ therapy developed S. aureus bacteremia or nonbacteremic infections, compared to 5 of 52 who received IL-2." (PMID 27093273, 2016). "Moreover, fatigue was associated with some immunotherapies for HIV/AIDS, such as interferon (IFN)-α and IL-2; about half of 317 patients living with HIV/AIDS reported high levels of fatigue." (PMID 26435495, 2015). "In HIV/AIDS, IL-2 production is frequently used to assess T cell immunity since IL-2 producing CD8+ T cells are found in very low frequencies in viremic individuals progressing rapidly to AIDS, compared to long-term non-progressors." (PMID 24918932, 2014). "There was only one AIDS-defining event which was Kaposi's sarcoma diagnosed at week 32 and only one HIV-related event, oral hairy leukoplakia at week 42, both in patients with prior IL-2." (PMID 20687947, 2010). "The study showed that IL-2 significantly expanded CD4 cell numbers, did not increase HIV-1 RNA levels and appeared to reduce the number of AIDS-defining events." (PMID 20687947, 2010). "Thus, IL-2 expansion of CD4+ Treg cells in HIV patients could not be expected to cure the deficit in conventional T cells seen in this disease nor contribute to decreasing the incidence of opportunistic infections and AIDS or non-AIDS-related malignancies." (PMID 22383042, 2012).